TNF (tumor necrosis factor)
Diseases named in the same sentence as TNF in open-access papers (continued):
Sharing a sentence is not in itself a finding about the gene and the disease.
liver fibrosis (continued). "Given the prominent role of inflammatory cytokine signaling in liver fibrosis and TNFα-induced NLRC5 expression in the human HSC cell line LX-2, Li and colleagues investigated the role of NLRC5 in modulating the fibrogenic response in HSCs." (PMID 34712238, 2021). "Compared to the positive control group, treatment of RBO at both dosage levels (0.2 and 0.4 mL/rat) for two weeks after development of liver fibrosis made a considerable reduction in liver content of TNF-α, IL-1β, and NF-κβ." (PMID 34965258, 2021). "Among them, NF-κB induces the expression of pro-inflammatory cytokines, such as TNF-α and IL-1β, which produces the cytotoxic environment, thereby further triggering the development of chronic inflammation and progressive liver fibrosis." (PMID 34867416, 2021). "That said, studies in murine models have shown TNF to be an important mediator of granuloma formation and hepatic fibrosis, however, clear distinction between granuloma formation and PPF has to be drawn as we do not know how the two relate." (PMID 33790908, 2021). "Cytokines such as platelet-derived growth factor, transforming growth factor-β (TGF-β), TNF-α, and Interferon also play a crucial role in the pathogenesis of liver fibrosis and cirrhosis." (PMID 34803712, 2021). "In order to verify that the effect of CGEA on liver fibrosis in experimental rats is achieved by reducing liver inflammation, we determined the levels of IL-6 and TNF-α in rat liver tissue using the ELISA method." (PMID 33995112, 2021). "Upon TLR activation, cells produce proinflammatory cytokines such as TNF-α, IL-6, IL-1, and monocyte chemoattractant protein-1, which further contribute to liver fibrosis." (PMID 34422075, 2021). "The levels of the NF-ΚB signalling pathway activation markers TNF-α, IL-1β and phospho-p65 were increased by CssPLA2 in the context of liver fibrosis." (PMID 33691755, 2021). "In order to further investigate the efficacy of liposomal SPB extract, we assessed the expression levels of inflammatory cytokines (IL-1 and TNF-α) and liver fibrosis genetic markers (TGF-β and SM-α)." (PMID 34707781, 2021). "In cattle, liver fibrosis has been proposed as a downstream effect of upregulated TNF and IL1B, which would activate the genes that were also upregulated in the bovine study, i.e., IL6, PLAU, SERPINE1, TNFRSF1A, SOCS1, and CTSB." (PMID 34616397, 2021). "The findings of this study demonstrated that TNFRII-Fc protein-mediated inhibition of TNFα signalling protects the human myotubes or mouse skeletal muscle tissues against atrophy induced by the liver fibrosis." (PMID 33414474, 2021). "Algandaby also showed that crocin (25 and 100 mg/kg) attenuates the expression of TGF-β, alpha-smooth muscle actin (α-SMA) and collagen 1-α, NF-κB, COX-2, IL-1β, and TNF-α following thioacetamide-induced liver fibrosis in mice." (PMID 34956439, 2021). "In hepatic fibrosis, pro-inflammatory cytokines, including IL-1, IL-6, and TNF-α, generated by Kupffer, hepatocytes, and infiltrating inflammatory cells promote liver damage." (PMID 34764877, 2021). "Systemic inflammation is another key indicator of the pathogenesis of liver fibrosis, and IL-6, TNF-α, and TGF-β are the main cytokines in this pathological condition." (PMID 34549998, 2021). "On the other hand, NASH patients showed strong and positive correlations between IL-12 and TNF with the NAFLD liver fibrosis score, CAP, and Kpa (transient elastography)." (PMID 34447378, 2021). "TNFα, expressed by macrophages and hepatocytes in response to toll-like receptor signaling, contributes to liver fibrosis by activating HSC and immune cells." (PMID 34712238, 2021). "Tumor necrosis factor-α is a multifunctional cytokine contributing to chronic progress of liver inflammation that accounts for liver fibrosis." (PMID 34965258, 2021).
liver fibrosis (continued). "For instance, in collaboration with TNF-α, IL-17 promotes HepG2 cells to produce more periostin, which induces fibroblasts to synthesize additional type I collagen and aggravate liver fibrosis." (PMID 33869241, 2021). "The expression of TNF-α noticeably increased in the hepatocytes surrounding the central vein and the hepatocytes surrounding the portal area upon induction of liver fibrosis." (PMID 34778375, 2021). "For example, capsaicin shows liver fibrosis progression by regulating Notch signaling to reduce secretion of inflammatory cytokine TNF-α, which attenuates myofibroblast regeneration and fibrosis mediated by HSCs." (PMID 34805276, 2021). "After that, the effective rate of treatment, the incidence of adverse reactions, liver function indexes, liver fibrosis condition, and TNF-α and IL-6 expression levels were all compared between the two groups." (PMID 34484339, 2021). "The results of the present study revealed that melatonin, IL-6, and TNF-α levels have a significant increasing trend with the progression of liver fibrosis." (PMID 34221262, 2021). "TNF-α and IL-6 are proinflammatory factors with the synergistic effect, which can promote the progress of liver fibrosis and inflammation in patients, while the incidence of adverse reactions in patients is the key index to evaluate the effect of drug therapy." (PMID 34484339, 2021). "Melatonin (MT) demonstrates an antioxidant effect in protecting cells and tissues from radical damage, while also inhibiting pro-inflammatory cytokines including TNF‐α, IL‐1β, and IL‐6 b during the development of hepatic fibrosis." (PMID 34221262, 2021). "Following induction of liver injury by CCl4 or other stimulators, a variety of cells generate proinflammatory cytokines, including TNF-α and IL-1β, to promote liver fibrosis." (PMID 34276360, 2021). "In conclusion, this study demonstrated that circulating TNFα, which is released from the fibrotic liver, promotes the atrophy of skeletal muscles during liver fibrosis." (PMID 33414474, 2021). "In chronic liver injury, LSECs undergo capillarization, they downregulate eNOS and NO synthesis, and they secrete profibrogenic and proinflammatory cytokines such as TGF-β1, PDGF, TNF-α and IL-6, thereby promoting liver fibrosis." (PMID 34805276, 2021). "These inflammatory factors contribute to the progression of liver fibrosis, while TNF-α can stimulate collagen synthesis and IL-6 and IL-1β can activate hepatic stellate cells and directly stimulate collagen secretion." (PMID 34899328, 2021). "The NF-κB signalling pathway is associated with a variety of inflammatory responses, such as TNF-α secretion, which regulates the activation or apoptosis of HSCs during liver fibrosis." (PMID 33691755, 2021). "IFN-γ is important in the protective mechanism against hepatic fibrosis, while TNF can aggravate the pathogenesis, due to its roles in activating hepatic stellate cells and collagen deposition." (PMID 33815321, 2021). "Inflammatory cytokines such as TNFα and the fibrogenic cytokine TGFβ play key roles in the pathogenesis of liver fibrosis." (PMID 34712238, 2021). "The key producer cells of TNF during liver fibrosis are activated liver-resident Kupffer cells and monocyte-derived macrophages, which are recruited by chemokines expressed in the inflamed liver." (PMID 34712238, 2021). "MaR1 restores the enhanced levels of TNF-α and normalizes the apoptosis evidenced in liver fibrosis." (PMID 34943914, 2021). "Next, through the feedback mechanism, the secretion of a large number of proinflammatory cytokines, such as IL-1β and TNF-α, is increased, which further promotes liver steatosis, inflammation, and liver fibrosis." (PMID 34095305, 2021). "Engulfment of apoptotic bodies by KCs enhances expression of death ligand Fas and pro-inflammatory cytokine TNF-α, thus accelerating hepatocyte apoptosis and provoking hepatic inflammation resulting in hepatic fibrosis." (PMID 34064375, 2021).
liver fibrosis (continued). "In experimental liver fibrosis, IL-17A activates both HSCs and KCs, and stimulates TNF-α, IL-6 and TGF-β secretion that further aggravate fibrosis." (PMID 34064375, 2021). "The levels of TNF-α, IL-1β, phospho-p65 and other NF-κB signalling markers were increased in the progression of liver fibrosis." (PMID 33691755, 2021). "SNS treatment additionally inhibited hepatic parenchyma cell apoptosis in liver tissues of mice with liver fibrosis and regulated apoptin expression while protecting L02 cells against apoptosis induced by TNF-α and Act D in vitro." (PMID 34276360, 2021). "Decrease in liver fibrosis in rats exposed to carbon tetrachloride.They attenuate proinflammatory TNF-α signaling and gene expression in mice liver." (PMID 33868227, 2021). "Based on network pharmacology results, apoptosis, inflammation and angiogenesis, together with the associated pathways (including VEGF, TNF, caspase, PPAR-γ and NF-κB), were identified as the mechanisms underlying the effects of SNS on liver fibrosis." (PMID 34276360, 2021). "Choi reported that treatment with 50–200 mg/kg anthocyanins significantly decreased DMN-induced enhancement of α-SMA and collagen types I and III levels in a liver fibrosis model, as well as TNF-α and TGF-β." (PMID 33082829, 2020). "Based on results of network pharmacology, it was known that flavonoids can possibly suppress liver fibrosis by inhibiting the IL-17 signaling pathway, which includes NF-κB, AP-1, IL-6, IL-1β, TNFα, IFN-γ, CCL2, COX2, MMP1, MMP3, and MMP9." (PMID 33551818, 2020). "Our study indicated that SP effectively reduces the expression of TNF-α protein in liver fibrosis in mice induced by CCl4." (PMID 32932919, 2020). "Cluster1 had a beneficial anti-immune response (higher IFN-γ, TNF-α and DNA damage repair response, leukocyte fraction and lower reactive stroma and angiogenesis), despite high levels of gene modules in hepatic fibrosis, proliferation and differentiation." (PMID 32509418, 2020). "ER stress in KCs reduced the levels of liver function markers, reduced the degree of liver fibrosis, and increased the number of KCs with the M1 phenotype and the expression of TNF-α." (PMID 32802876, 2020). "The results demonstrated that RTA and RTB inhibited the production of NO, TNF-α, and IL-6 and suppressed liver fibrosis." (PMID 33224259, 2020). "It was reported before that iNOS and TNF-α expression was highly up-regulated in inflammatory disorders like hepatic fibrosis and attenuated with the treatment." (PMID 32357508, 2020). "A series of studies from Ling's team suggested that 800 mg/kg dietary cyanidin-3-O-β-glucoside alleviated liver fibrosis by suppressing inflammatory factors, such as TNF-α, IL-6, and IL-10." (PMID 33082829, 2020). "TNF-α can directly promote the apoptosis of or inhibit the proliferation of HSCs, especially in a chronic hepatic fibrosis model." (PMID 32802876, 2020). "The release of EGFR ligands by HSCs can have pro- as well as anti-fibrotic activities, depending on the ligand, while the release of TNFα promotes liver fibrosis." (PMID 32698506, 2020). "Impressively, this combination also remarkably inhibited the pre-inflammatory mediators release of IL-6 and TNF-α, which provides a specific target in the screening of anti-inflammatory drugs for the treatment of schistosomiasis-induced liver fibrosis." (PMID 33553120, 2020). "Leptin administration has been shown to enhance liver fibrosis by increasing the expression of procollagen-I, TGFβ1 and smooth muscle actin and amplify inflammation by increasing the systemic levels of TNF-α in experimental models." (PMID 32933141, 2020). "TNFα also appears to be a key mediator of fatty liver disease and hepatic fibrosis, so (TNFi) has been proposed as a potential therapeutic target for patients with NASH." (PMID 32494263, 2020).
liver fibrosis (continued). "HSCs lacking Rhbdf2 that is required for ADAM17 maturation, displayed reduced TNFR1 and 2 shedding and as a consequence of enhanced TNF signalling, Rhbdf2-/- mice displayed enhanced bile duct obstruction-induced liver fibrosis." (PMID 32698506, 2020). "Pradere and colleagues confirmed that TNF-α and IL-1β accelerated liver fibrosis by promoting the survival of activated HSCs in vitro and in vivo." (PMID 33117360, 2020). "TNF-α can induce neutrophil infiltration and stimulate mitochondria of apoptotic hepatocytes to generate oxidants, which further aggravate liver fibrosis." (PMID 32932919, 2020). "Many small molecules are important triggers of liver fibrosis, such as tumor necrosis factor-alpha (TNF-α), interleukin-10 (IL-10), and transforming growth factor-beta (TGF-β), which possess effective pro-inflammatory or anti-inflammatory effects." (PMID 32226380, 2020). "Our results showed that the macrophages were significantly accumulated in the pulmonary alveolar and the interval space in the rat models of liver fibrosis, with elevated levels of TNF-α in the homogenate." (PMID 33817199, 2019). "Taken together, our results suggest that the injection of etanercept-secretome protects the liver against inflammatory and fibrotic damages by inhibiting TNF-α-driven inflammation during liver fibrosis." (PMID 31847135, 2019). "On the contrary, there are also reports that TNF-α protects the liver from damage, promotes liver regeneration, and ameliorates liver fibrosis by inhibiting the expression of collagen type 1 alpha 1 chain (COL1A1) in HSCs." (PMID 31847135, 2019). "TNF-α is released during the inflammatory phase of liver fibrosis, and plays a decisive role in the progression of liver fibrosis by activating HSCs to secrete fibrogenic materials." (PMID 31847135, 2019). "Knocking out dectin-1 exacerbated liver fibrosis and inflammation, as demonstrated by increased expression of TNF-α, IL-6, and MCP-1, neutrophil and macrophage influx, and fibrosis progression." (PMID 31717860, 2019). "During cholestasis, excessive inflammatory responses can activate the TLR4 signaling pathway, which promotes NF-κB activation to secrete more proinflammatory cytokines, like TNF-α and IL-6, to aggravate inflammatory damage and liver fibrosis." (PMID 31827690, 2019). "In conclusion, we showed that the use of etanercept-secretome is capable of considerably ameliorating liver fibrosis by blocking TNF-α because TNF-α plays a crucial role in the inflammatory response in the liver fibrosis process." (PMID 31847135, 2019). "Liver function (Serum levels of AST, ALT and CK-18 M30; steatosis and fibrosis of liver), serum levels of TNF-α, MDA, and adiponectin will be measured at the baseline and the end of trial for both groups and their results will be compared." (PMID 31324181, 2019). "Compared to the untreated liver fibrosis group, the expression of inflammatory factors including IL-1, IL-2, IL-6, IL-8, IL-10, and TNF-α were significantly decreased in the hBM-MSCs and hBM-MSCs-Ex treatment groups (p < 0.05)." (PMID 30885249, 2019). "Tumor necrosis factor-α (TNF-α) is one of the predominant cytokines involved in all these steps leading to liver fibrosis." (PMID 31847135, 2019). "Our observations that CCl4 injection induced elevation of IFN-γ, TNF-α, and IL-6 and aggravation of liver fibrosis in this study are consistent with these previous conclusions." (PMID 30635047, 2019). "On the other hand, the intensification and progression of liver fibrosis is related to the enhancement of TNF-α and IL-6 levels in the liver." (PMID 32128089, 2019). "The TNF pathway, containing caspases, pro-apoptotic and anti-apoptotic members, is involved in liver fibrosis." (PMID 30669350, 2019). "Studies have also demonstrated that TNF-α and IL-6 play important roles in the development of liver fibrosis." (PMID 30635047, 2019).
liver fibrosis (continued). "Tumor necrosis factor-α (TNF-α)-driven inflammatory reaction plays a crucial role in the initiation of liver fibrosis." (PMID 31847135, 2019). "Injection of etanercept-secretome also resulted in the significantly lower serum levels of liver enzymes as well as pro-inflammatory cytokines, such as TNF-α and IL-6, in the mice with liver fibrosis." (PMID 31847135, 2019). "Our results suggest that the administration of etanercept-secretome improves liver fibrosis by inhibiting TNF-α-driven inflammation in the mice with liver fibrosis." (PMID 31847135, 2019). "Both TNF-α and IL-6 are involved in the conversion of HSCs into myofibroblasts that contribute to liver fibrosis." (PMID 30096951, 2018). "Leptin can promote an inflammatory response by activating the secretion of proinflammatory cytokines, such as TNF-α, IL-6, and IL-12 in liver fibrosis." (PMID 29436483, 2018). "Overall, adding to observations in experimental models, a strong case is made for INF-ɤ as an anti-fibrotic cytokine, whereas TNF-α (also produced by Th1 cells and macrophages) primarily appears to aggravate hepatic fibrosis during schistosomiasis." (PMID 30546364, 2018). "Both curcumin prevention and treatment reduced molecular markers of hepatic fibrosis (Col1a1 mRNA) and inflammation (TNF‐α, SPP1 mRNA)." (PMID 30009570, 2018). "Significant increase in NF-κB p50, NF-κB p65, TNF-α and IL-6 mRNA expressions were detected in CCl4-induced liver fibrosis in mice, compared to control." (PMID 30150935, 2018). "The generation of ROS, tumor necrosis factor-α, TGF-β, and PDGF can be implicated as a cause of hepatic fibrosis." (PMID 30627538, 2018). "Of the various kinds of inflammatory mediators TNF-α plays an important role in the pathogenesis of liver fibrosis through activation of Kupffer cells." (PMID 29891794, 2018). "In the microenvironment of liver fibrosis, secreted IL-1β and TNF-α have been shown to promote the survival of activated HSCs and increase the inflammation reaction." (PMID 28871223, 2017). "TNF-α blockade protects ERG expression and reduces phosphorylation of SMAD2/3 in an acute model of liver fibrosis, but is ineffective in ERG hemi-deficient mice." (PMID 29026072, 2017). "Positively correlation between hepatic TSPO and (transforming growth factor) TGF-β1/(tumor necrosis factor) TNF-α mRNA expression suggests that macrophage M1 and M2 phenotypes intervene during liver fibrosis development." (PMID 29114179, 2017). "TNF-α also increases liver fibrosis by promoting activated HSCs to produce a large number of ECM proteins and to secrete several soluble cytokines, such as TGF-β, IL-1, IL-6, VEGF and ET-1." (PMID 28358817, 2017). "Secondly, the long-term low dose treatment with Sch B was shown to reduce hepatic TG levels, FAS activity, levels of SREBP1 and TNF-α, and the extent of hepatic fibrosis in HFD-fed mice." (PMID 27847552, 2016). "There was a clear positive connection of IL-10 with the TNF node in patients with mild liver fibrosis, whereas there is an evident inverse correlation between IL-10 with all other cytokine nodes." (PMID 26742960, 2016). "Experiments in a variety of models and diseases have shown that TNF-α accentuates liver fibrosis by increasing hepatocellular damage." (PMID 27046197, 2016). "Despite the lower frequency of intrahepatic T-cells and scarce frequency of Tregs, patients with severe liver fibrosis showed higher levels of proinflammatory cytokines (TNF and IFN-γ)." (PMID 26742960, 2016). "Out study showed that treatment with anti-IL-9Ab and anti-IL-17Ab exerted similar effects on suppressing plasma secretion and liver expression of TGF-β1, IL-6, TNF-α, IL-4 and IL-9 in mice with liver fibrosis." (PMID 26728971, 2016). "Anti-IL-9Ab treatment sharply decreased plasma concentrations of TGF-β1, IL-6, IL-4, and TNF-α in a mouse model of liver fibrosis." (PMID 26728971, 2016).